CLU (clusterin)
Diseases named in the same sentence as CLU in open-access papers (continued):
Sharing a sentence is not in itself a finding about the gene and the disease.
prostate carcinoma (continued). "Likewise, overexpression of CLU enhances the metastatic ability of human renal cell carcinoma 21 and prostate cancer." (PMID 33052230, 2020). "Moreover, CLU gene silencing in human bladder and prostate cancers inhibited growth and increased their chemosensitivity." (PMID 26988917, 2016). "HMGB1 induced clusterin protected prostate cancer cells from docetaxel, an antitumor drug." (PMID 26925422, 2016). "Multiple studies supported that CLU inhibition might represent a promising therapeutic option for suppressing metastatic progression of prostate cancer." (PMID 25609201, 2015). "In addition, CLU expression in an androgen-dependent prostate cancer cell line was shown to increase in a time- and dose-dependent manner after androgen treatment both at mRNA and protein levels." (PMID 25884309, 2015). "Overexpression of CLU in OS indicates drug resistance to conventional therapies and over-expression of CLU in prostate cancer cells accelerates progression after hormone- or chemo-therapy, identifying CLU as an anti-apoptotic gene up-regulated by treatment stress that confers therapeutic resistance." (PMID 25138053, 2014). "Moreover, inhibition of autophagy attenuated CLU-mediated cytoprotection in prostate cancer cell lines, suggesting that CLU supports cancer cell survival partially via autophagy-dependent pathways." (PMID 25503391, 2014). "Furthermore, CLU-mediated cytoprotection involves autophagy activation, since the cytoprotective effect of CLU in prostate cancer cells was lost when autophagy was inhibited." (PMID 25503391, 2014). "Indeed, autophagy induction was dramatically reduced in CLU−/− mice, while CLU silencing in prostate cancer cell lines significantly inhibited stress-induced LC3 puncta and enhanced treatment-induced apoptosis." (PMID 25503391, 2014). "The expression status of CLU might change in many human cancers, such as gastric cancer, colon cancer, pancreatic cancer, prostate cancer, breast cancer, lung cancer and renal cell carcinoma." (PMID 24143209, 2013). "Similarly, clusterin expression in prostate cancer has been correlated with the Gleason tumor grade, and is believed to compromise survival by inhibiting apoptosis after hormonal ablation therapy." (PMID 22799602, 2012). "Quantitative reverse transcriptase PCR (Q-PCR) and immunohistochemistry (IHC) showed a very efficient dose dependent inhibition of clusterin mRNA (>90% at the maximum dose) and protein (complete suppression in 57% of cells at the maximum dose) in prostate cancer tissue." (PMID 22989709, 2012). "Moreover, changes in clusterin levels are being studied as surrogate biomarkers for treatment efficacy in clinical trials of anti-clusterin therapy in breast, lung and prostate cancer." (PMID 19348683, 2009). "Besides a variety of colon carcinoma cell lines, we also included a number of prostate carcinoma cell lines in our analysis since CLU has been reported to be up-regulated in this cancer type." (PMID 17634137, 2007). "This could have significance for the resistance of prostate cancers to chemo/radiotherapy, where clusterin overexpression is observed." (PMID 15494717, 2004). "In addition, clusterin appears to contribute to an anti-apoptotic environment in prostate cancer cells, potentially influencing Bcl-2 activity and leading to increased cell survival, although the direct activation of Bcl-2 by clusterin has not been fully established." (PMID 38535120, 2024). "Many factors indicate that clusterin is involved in the mechanism of regulation of contrary processes such as cell survival and apoptosis, which has been observed both in colon cancer and other types of cancer, e.g., bladder cancer, kidney cancer, and prostate cancer." (PMID 36071866, 2022).
prostate carcinoma (continued). "Elevated serum clusterin levels have been observed in the course of many different human disorders, such as diabetes, coronary heart disease, psoriasis, chronic spontaneous urticaria, septic shock, and several neoplastic diseases, e.g., colorectal cancer or prostate cancer." (PMID 31940868, 2020). "We show that forced clusterin expression in LβT2 and αT3 pituitary gonadotroph cells triggers a linage-specific cytostatic response, inducing p15, p16, or p27; decreased cell proliferation was also evidenced by lower expression of pH 3, similar to observations in prostate cancer cells." (PMID 21464964, 2011). "In this study, we showed that apoptosis in prostate cancer cells can be regulated by three genes important for cell survival, HSP27, cFLIP, and CLU." (PMID 38535120, 2024). "In LNCaP prostate cancer cells, reduced expression of SAM68 altered the expression of an important subset of genes involved in proliferation and apoptosis, including Bcl2L1, Clusterin, cdk2, cdk3, p16INK4, cyclin D1, Par-4, EGF and IGF-1." (PMID 25944080, 2015). "The expression of five prostate cancer related proteins (AR, HSP27, CLU, GRP78, and c-FLIP) increased in ls-LNCaP compared with es-LNCaP (AR, 157%; HSP27, 132%; CLU, 146%; GRP78, 138; and c-FLIP, 152%)." (PMID 23476140, 2013). "Among the four experimental cell lines (es-LNCaP, ls-LNCaP, scr-ls-LNCaP, and si-ls-LNCaP), we confirmed the expression level of five prostate cancer related proteins (AR, HSP27, CLU, GRP78, and c-FLIP) with immunocytochemical staining." (PMID 23476140, 2013). "Moreover, in prostate cancer, IGF-1 enhances the transcriptional activity of the CLU gene by activating the STAT-3/Twist-1 axis." (PMID 38667280, 2024). "Among the targets negatively regulated by E6AP is the stress-induced chaperone clusterin (CLU), which may play a tumor-suppressive role in prostate cancer." (PMID 32751183, 2020). "In fact, apart from CLU, also CEBPB and D seem to play a role in PC proliferation, as interleukin-6 (IL-6) treatment increases the expression of CEBP-D family member, inducing IL-6/STAT3-dependent growth arrest on prostate cancer cells in vitro." (PMID 29562723, 2018). "CLU inhibition using its targeted inhibitor (OGX-011) synergistically enhanced the activities of Hsp90 and androgen receptor inhibitor in castrate-resistant prostate cancer." (PMID 25609201, 2015). "Clusterin was shown to dramatically enhance the migratory and invasive behavior of the normal prostate epithelial cell line PNT1A and the prostate cancer cell line PC3 by regulating the miR-190-5p-PHLPP1 axis, suggesting that miR-190-5p functions as an oncogene in prostate cancer." (PMID 31624470, 2019). "We use non-malignant HEK‐293 cells as well as prostate cancer (PC‐3), mammary gland carcinoma (MCF‐7) and colorectal adenocarcinoma cells (Caco‐2) since expression of intracellular CLU isoforms and/or different CLU mRNA variants has been reported in these cells and for these types of cancer." (PMID 24073260, 2013). "However, stress-induced increase in several antiapoptotic genes, such as bcl-2, clusterin, insulin-like growth factor binding protein-2 (IGFBP-2), IGFBP-5 and heat-shock protein 27, have been shown to have important functions in the AI progression of prostate cancer after castration." (PMID 19844233, 2009).
breast carcinoma (48 papers, 2007 to 2026). "It has been documented that CLU levels are associated with breast cancer development and correlate with tumor stage, lymph node metastasis, and disease-free survival as well as overall survival." (PMID 36071866, 2022). "In breast cancer, overexpression of CLU was also associated with resistance to neoadjuvant chemotherapy." (PMID 33187552, 2020). "The upregulated expression of CLU was associated with highly aggressive breast carcinoma and with tumor progression and recurrence in bladder cancer." (PMID 26988917, 2016). "The results from this study are also in agreement with the findings showing increased CLU transcript variants expression in hormonally regulated human cancers, such as prostate and breast carcinomas." (PMID 25934174, 2015). "In cases of the non small cell lung and breast cancers, the expression of CLU was demonstrated to be significantly associated with relapse-free and metastasis-free survival of patients." (PMID 19709441, 2009). "Overexpression of the apoptosis-related protein clusterin is associated with breast cancer development and tumor progression." (PMID 18078515, 2007). "Increased expression of the clusterin gene has been observed in breast cancer cells and has been associated with the development and progression of these tumors." (PMID 18078515, 2007). "Dexamethasone pretreatment of breast cancer cell lines is associated with the transcriptional induction of clusterin." (PMID 18078515, 2007). "We also demonstrate that dexamethasone pretreatment of breast cancer cell lines inhibits chemotherapy-induced cytotoxicity and is associated with the transcriptional induction of clusterin." (PMID 18078515, 2007). "Clusterin expression is altered in different cancers, including overexpression in human breast carcinoma, which is associated with increased tumor size, progesterone receptor-negative status, and the progression from primary to metastatic carcinoma in lymph nodes." (PMID 28210565, 2017). "The studies described here are designed to investigate whether secretory clusterin expression plays a causative role in the progression of human breast carcinoma." (PMID 20307318, 2010). "Moreover, glucocorticoid activation in breast cancer cells regulates survival signaling by the direct transactivation of genes like clusterin which encode proteins that decrease susceptibility to apoptosis." (PMID 18078515, 2007). "In breast cancer, two small retrospective studies has shown an association with elevated clusterin expression and large tumor size, estrogen and progesterone receptor status and with the progression from the primary carcinoma to metastatic carcinoma in lymph nodes in breast cancer." (PMID 20307318, 2010). "Taken together, our results identify a targetable a clinically accessible PKP3-clusterin axis that disrupts circadian gene expression in fat tissue in breast cancer." (PMID 41408487, 2025). "On the other hand, studies conducted on different tissues, including breast cancer cells, ovarian epithelial cancer cells and rat fibroblast cells, confirmed the correlation between CLU expression and its promoter methylation status." (PMID 37685987, 2023). "In breast cancer, CLU has been shown to enhance the effects of eHsp90α in activating important protein families, including Akt, ERK and NF-κB." (PMID 37685987, 2023). "For example, nCLU, a nuclear isoform of CLU, binds Ku70 and triggers apoptosis in the breast cancer cell line MCF-7 by freeing Bax." (PMID 35626071, 2022). "The disturbance of blood plasma clusterin expression has been documented in many types of cancer, including breast cancer." (PMID 36071866, 2022). "For example, bone-marrow-derived CAFs in breast cancer were shown to express high levels of Clusterin (Clu), and exhibit a distinct transcriptional profile compared to tissue-resident CAFs40." (PMID 36316305, 2022).
breast carcinoma (continued). "In vivo co-administration of eHSP90α and Clusterin in mice carrying breast cancer cells derived tumors significantly increases metastasis." (PMID 34722515, 2021). "In breast cancer cells, CLU favors the binding of eHSP-90α to the surface receptor LRP-1 and potentiates the transduction of EMT-promoting signaling." (PMID 34360868, 2021). "CLU is one of the most significantly upregulated genes in the murine breast cancer cell line BRI-JM01, undergoing TGFβ-induced EMT, where its neutralization with an anti-CLU antibody blocks the acquisition of the mesenchymal phenotype induced by TGFβ." (PMID 34360868, 2021). "In breast cancer cells, clusterin (CLU) was identified as a novel target gene of BHLHE40 and suppressed DNA damage-induced cell death." (PMID 32577154, 2020). "Clusterin was present at higher levels in both fractions of patients with early and intermediate stages of breast cancer." (PMID 28210565, 2017). "The level of clusterin expression correlated with the level of estrogen and progesterone receptor expression, tumor size, and lymph node metastasis in breast carcinoma." (PMID 26293319, 2015). "In hepatocellular carcinoma, lung adenocarcinoma and breast cancer cell lines, CLU silencing has similarly showed a decrease in cell motility, invasion and metastasis." (PMID 26399194, 2015). "Clusterin overexpression has been shown in various human malignancies including cancer of the breast, pancreas, and colon." (PMID 22957256, 2012). "Clusterin overexpression has been reported to be marginally related to early recurrence and shorter survival in breast cancer, especially in early stage disease, and has been shown to increase resistance to anti-estrogen hormonal therapy." (PMID 22799602, 2012). "Clusterin also induces breast cancer cell growth and metastatic progression and is associated with human lung adenocarcinoma cell growth." (PMID 21464964, 2011). "CLU expression levels correlated with tumor size, estrogen and progesterone receptor expression levels, and lymph node metastasis in breast carcinoma." (PMID 22185350, 2011). "The data presented here demonstrate that over-expression of secretory clusterin alters the phenotypic behavior of MCF-7 breast cancer cells." (PMID 20307318, 2010). "In MCF-7 breast cancer cells, the biogenesis of clusterin is significantly altered during tamoxifen-induced apoptosis, and a new isoform of the protein appears in the nucleus." (PMID 20307318, 2010). "Using an orthotopic model of breast cancer, we have also determined the effects of over-expression of clusterin on tumor growth and metastatic progression." (PMID 20307318, 2010). "We describe the use of clusterin-specific antisense oligonucleotides and antibodies to sensitize breast carcinoma cells to anticancer drugs routinely used in breast cancer therapy." (PMID 18078515, 2007). "RT-PCR analysis was used to determine the effect of treatment with antisense clusterin ODN on clusterin RNA expression in breast carcinoma cells." (PMID 18078515, 2007). "Time course experiments in breast cancer cells demonstrated that clusterin RNA upregulation peaked as early as 4 to 8 hours after treatment." (PMID 18078515, 2007). "RT-PCR analysis was also used to determine the effects of chemotherapeutic agents and tamoxifen on clusterin RNA expression in breast cancer cell lines." (PMID 18078515, 2007). "The present study confirms in the estrogen receptor-positive breast cancer cell line MCF-7 that clusterin levels increase after treatment with tamoxifen and dexamethasone." (PMID 18078515, 2007). "In breast carcinomas, overexpression of clusterin is significantly associated with a negative expression of estrogen and progesterone receptor status." (PMID 37685987, 2023). "In breast carcinoma, the expression of clusterin increases as the tumor progresses." (PMID 37685987, 2023). "Up-regulation of clusterin in breast cancers has been previously reported, but whether serum sCLU is enhanced still unknown." (PMID 33356806, 2021).
breast carcinoma (continued). "The levels of clusterin (CLUS_HUMAN) were increased in the plasma of patients with breast cancer." (PMID 28210565, 2017). "Conversely, our expression profile results showed that some genes such as histone 2, and those known to regulate DNA synthesis (CTP synthase) and apoptosis (clusterin), were oppositely regulated by belinostat compared to other reports that used different HDACIs on bladder and breast carcinoma cells." (PMID 17935615, 2007). "However, as compared with normal tissues, the clusterin decreased in lung cancer (5.6±2.1 vs. 10.8±1.6, p = 0.005), breast cancer (7.1±2.7 vs. 10.5±1.7, p = 0.017), and ovarian cancer (6.8±3.0 vs. 10.5±1.7, p = 0.011)." (PMID 17989776, 2007). "We suggest that glucocorticoids may influence breast cancer behavior via the upregulation of clusterin, which might play a major role in the effects of dexamethasone, protecting breast cancer cells from the effects of both paclitaxel and doxorubicin." (PMID 18078515, 2007). "In addition, antibodies targeting clusterin, a stress-activated and apoptosis-associated molecular chaperone also overexpressed in breast cancer, have been reported to inhibit TGF-β-induced EMT and to reduce lung metastasis in breast cancer models." (PMID 31330794, 2019). "Using this methodology, we identified nine proteins—FN1, VWF, PRG4, MMP9, CLU, PRDX6, PPBP (CXCL7), APOC1, and CHL1—that were robustly quantified in serum and showed statistically significant differences between breast cancer patients and healthy controls." (PMID 40940928, 2025). "The Clusterin/HSP90α complex binds to LRP1 with higher affinity in respect to eHP90α alone and potentiates the signal, increasing breast cancer cell migration." (PMID 34722515, 2021). "CLU and YB-1 silencing similarly modulates TNT formation in MCF7 breast cancer cells under stress conditions, indicating a broader role of these stress adaptor proteins on TNT formation in other cancers." (PMID 31127190, 2019). "Previous studies found CLU regulates aggressive behavior andchemosensitivity through modulating ERK1/2 signaling in pancreatic cancer, breast cancer, and lung cancer cells." (PMID 25106434, 2014). "To investigate the role of secretory clusterin in the biology of breast cancer tumor growth and resistance to therapy we have engineered an MCF-7 cell line (MCF-7CLU) that over-expresses clusterin." (PMID 20307318, 2010). "Genes of known importance in breast cancer and estrogen signaling, including ERBB2, PGR, MYC, CLU, and NCOA2, were among those identified as Sin3A-responsive." (PMID 20920219, 2010). "Conversely, secretory CLU knockdown enhanced DNA damage-induced cell death in breast cancer cells, suggesting that BHLHE40 promoted cell survival by up-regulating secretory CLU to reduce the apoptotic response to DNA damage, providing insights into their roles in breast cancer progression." (PMID 40046513, 2025). "Reducing expression of antiapoptotic regulators such as cIAP 1, Bcl-2, catalase,clusterin, HO-1, livin, XIAP, HSP27 and claspin was also demonstrated in human breast cancer line; the latter in support of mithochondrial apoptotic pathway using bromelain-based CHCT." (PMID 34466585, 2020). "In sum, the loss of HDAC1 and HDAC2 increases C3 and NCOA2, but not CLU, ERBB2, MYC, or PGR, providing evidence that C3 and NCOA2 are repressed in breast cancer cells by the HDAC1/2 components of the Sin3A repressive complex." (PMID 20920219, 2010). "Breast cancer patients were reflective of their differential expression of serum α1-antichymotrypsin (ACT), clusterin (CLU) and complement factor B (CFB), while patients with nasopharyngeal carcinoma expressed the sole elevated levels of serum ceruloplasmin (CPL)." (PMID 18637207, 2008).
breast carcinoma (continued). "Although clusterin expression in normal breast epithelial cells is low or absent, it is very high in breast cancer cells during carcinogenesis and metastatic progression." (PMID 18078515, 2007).